CDK1 (cyclin dependent kinase 1)
Diseases named in the same sentence as CDK1 in open-access papers (continued):
Sharing a sentence is not in itself a finding about the gene and the disease.
pancreatic cancer (continued). "The results showed that CDK1 and CEP55 were significantly overexpressed in pancreatic tumorous tissues compared to normal tissues, which is consistent with the results in different datasets." (PMID 32587798, 2020). "Oncomine analysis of cancer vs. normal tissue indicated that CDK1 and CEP55 were significantly overexpressed in pancreatic cancer in different datasets." (PMID 32587798, 2020). "In the Grutzmann Pancreas dataset, CDK1 and CEP55 mRNA expression was higher in pancreatic cancer tissues than in normal pancreatic tissues." (PMID 32587798, 2020). "The growth of pancreatic cancer cell lines was reduced when CDC25B, an activator of CDK1, was inhibited resulting in accumulation of phosphorylated CDK1 and G2/M arrest." (PMID 30340359, 2018). "For example, it has been reported that inhibition of PPP2R1A radiosensitizes pancreatic cancer via activation of CDC25C/CDK1, thus, PPP2R1A is a target gene for local therapy of pancreatic cancer." (PMID 29697368, 2018). "In addition, Several CDK1 inhibitors, including Rigosertib (phase II/III) and Zotaraciclib, have begun phase I clinical trials for treating pancreatic cancer and glioma." (PMID 38605349, 2024). "In summary, CDK1 and STAT3, which are highly expressed in PDAC and PCSCs, are negatively correlated with the survival of PDAC patients and play an important role in maintaining pancreatic cancer stemness." (PMID 37743465, 2023). "CDK1, DSC2, ERO1A, MET, PYGL, and SLC35A3 were highly expressed while CHST12 was decreased in pancreatic cancer." (PMID 33912561, 2021). "Nonetheless, the relationship between CEP55 and CDK1 and the mechanism involved have not been studied in pancreatic cancer cells." (PMID 32587798, 2020). "Lastly, the eight snap-frozen tumorous and adjacent noncancerous adjacent tissues of pancreatic cancer patients used to detect the CDK1 and CEP55 protein levels by western blot." (PMID 32587798, 2020). "In SMAD4-negative pancreatic cancer cells treated with the compound UA62001, the cell cycle was interrupted in synthesis (S) and Gap 2 (G2) – mitotic (M) phases, whereas UA62784 activated CDK1 and induced mitotic cell-cycle arrest and apoptosis." (PMID 32429474, 2020). "The analytic results demonstrated that 7 upregulated (MMP9, CXCL8, ACTB, ITGB1, STAT1, TOP2A and CDK1) and 2 downregulated (GNMT and ABAT) hub genes may act as the key genes in pancreatic cancer." (PMID 31061236, 2019). "P276-00, a CDK1, CDK4, and CDK9 inhibitor, could sensitise pancreatic cancer cells to gemcitabine-induced apoptosis." (PMID 30340359, 2018). "Furthermore, it is also important to investigate the CDK1 phosphorylation status of YAP and to determine the correlation between CDK1/cyclin B activity and YAP phosphorylation in pancreatic cancer patients." (PMID 26440309, 2015). "To conclude, our present observations state that curcumin treatment potentially inhibits the proliferation of BxPC-3 human pancreatic cancer cells by DNA damage-mediated G2/M cell cycle arrest by the activation of ATM/Chk1/Cdc25C and inhibition of cyclin B1/Cdk1 expression." (PMID 19401701, 2009). "Furthermore, systemic administration of the multi-CDK inhibitor AT7519 (targeting CDK1/2/7/9) has shown favorable tolerability in pancreatic cancer xenograft models, with no significant adverse effects reported." (PMID 40695806, 2025). "Based on the transcriptomics profiling of anlotinib in this work and available pancreatic cancer related data deposited in TCGA, GEO, and ICGC databases, we further constructed a prognostic model which consists of five crucial genes, namely TOP2A, CRABP2, CDK1, NUSAP1, and PERP." (PMID 33748143, 2021). "Furthermore, CDK1 might phosphorylate TOP2A to promote S phase transition and influence the progression of pancreatic cancer, but follow-up research is needed to determine the specific mechanism of the interaction." (PMID 32587798, 2020).
pancreatic cancer (continued). "Last, we preliminarily validated the ChIP analyses by detecting CDK1 and CEP55 protein levels in eight snap-frozen tumorous and adjacent noncancerous adjacent tissues of pancreatic cancer patients." (PMID 32587798, 2020). "In the clinical specimens, CDK1 and CEP55 protein levels were significantly elevated in pancreatic cancer tissue samples compared with adjacent nontumor tissues." (PMID 32587798, 2020). "Previous studies have provided evidence about the expression of CDK1 and TOP2A in pancreatic cancer, but the correlation between them in pancreatic cancer has not been fully elucidated." (PMID 32587798, 2020). "Given that, the pharmacological inhibition of PIN1 and CDK1 could be promisingly used in the therapy of these cancers especially TNBC and pancreatic cancers featured with worse prognosis and no targeted therapies." (PMID 36813923, 2023).
glioma (64 papers, 2012 to 2026). A benign or malignant brain and spinal cord tumor that arises from glial cells (astrocytes, oligodendrocytes, ependymal cells). "Among cell cycle regulators, IDHwt gliomas were significantly more likely to have CDK1 loss and less likely to have cyclin A1 gene loss or cyclin D1 or E2 gene gain." (PMID 26091668, 2015). "Since CDK1 is associated with many types of human cancers, it is believed that CDK1 might play an important role in diagnosis and therapy of glioma." (PMID 30405856, 2018). "Interestingly, CASP3 and CYP1A1 were previously identified to be related to glioma and used to predict the survival for glioma patients, the high expression of CDK1 is associated with the malignant progression in glioma, and mutations in MT-CO1 contribute to brain tumours." (PMID 38642129, 2024). "Sixty glioma-associated targets were associated with CHR, such as MDR transporters (ABCB1, ABCC1, ABCG2), cyclin-dependent kinases (CDK1, CDK6), matrix metalloproteinases (MMP2, MMP9, MMP12), and genes related to inflammation or oxidative stress (NOS2, NOX4)." (PMID 40963691, 2025). "Although MYC and CDK1 were prioritized based on their consistent upregulation and well-established roles in glioma biology, it is likely that EGR3 governs a wider transcriptional network influencing multiple aspects of tumor progression." (PMID 40649712, 2025). "One possible explanation is that PKM2 interacts with the CDK1-cyclinB complex to facilitate cell cycle progression in gliomas, and knockdown of PKM2 decreases CDK1 kinase activity." (PMID 38390263, 2024). "Specifically, the relative expression levels of CDK1 and CyclinB1 were reduced, while in glioma cells, the expression levels of Wee1 and p21 were upregulated in GBM8401 cells." (PMID 37242425, 2023). "It has been reported that FOXD2-AS1 can promote cell proliferation in glioma through regulating FOXD2-AS1/miR-31/CDK1 axis." (PMID 37602882, 2023). "Western blot results revealed that following β-sitosterol treatment, the levels of cyclin B1 and CDK1 were reduced, and the effect was concentration dependent, indicating that β-sitosterol induced G2/M phase arrest in glioma cells." (PMID 38143380, 2023). "In our study, we found that OSW-1 inhibited the viability and proliferation of glioma cells and arrested cell cycle at G2/M by downregulating the expression of cycling B1 and CDK1 and upregulating the expression of P21." (PMID 36133816, 2022). "Upregulation of CDK1 promoted oncogenesis and progression of human gliomas, whereas downregulation of CDK1 and CDK2 expression inhibited the migration and invasion of human gliomas." (PMID 34953010, 2022). "It has been reported that gliomas can develop resistance to Temozolomide by immune escape through the CDK1/survivin signaling pathway." (PMID 35774141, 2022). "It promotes apoptosis in glioma cells by inducing G2/M cell cycle arrest by inhibiting the phosphorylation of CDK1 and the activity of the CDK1/cyclin B1 complex." (PMID 35694267, 2022). "It was reported that glioma cells can escape from TMZ-induced senescence through modulation of CDK1/Survivin signaling." (PMID 34100981, 2021). "Analysis of TCGA datasets in glioma patients confirmed significant positive correlation of ITGA6 expression with CDK1, CDK4, PCNA, and FOXM1 transcript levels." (PMID 34205341, 2021). "CDK1 is sensitive to HS in human neuroblastoma and glioma cell lines, and related to protein homeostasis in mammalian cells." (PMID 33920315, 2021). "Together, these findings indicate that inhibition of CDK1 sensitizes GBM cells to TMZ and suggest that targeting CDK1 is a potential mechanism to potentiate the anti-glioma effect of TMZ." (PMID 33707466, 2021). "It has been observed that in forced cell cycle arrest in the G2 phase (by observing the lower expression of G2 phase-specific proteins), the expression of SNORD47 significantly inhibits the proliferation of glioma cells and induces CyclinB1, CDK1, and CDC25C." (PMID 32977537, 2020).
glioma (continued). "There is also evidence that forced expression of cdk1-cyclin B attenuates drug sensitivity in glioma cells 20, and cyclin B overexpression in patients with head and neck squamous cell carcinoma has been correlated with poor therapeutic response." (PMID 25444514, 2015). "Concomitantly, 2OHOA led to the arrest of 1321N1 cells in the G2/M phase of the cell cycle, with down-regulation of cyclin B1 and Cdk1/Cdc2 proteins in the three glioma cell lines studied." (PMID 23133576, 2012). "Finally, we visualized the close association between CDCA3 and common glioma cell cycle checkpoint markers, including CDK6, CDK4, CDK2, CDK1, CDKN3, and CDKN2C, using circos plots." (PMID 38728485, 2024). "It has been documented that the expression of CDK1 is positively correlated with the grade of glioma, which may also increase with malignant progression after recurrence." (PMID 35677036, 2022). "To verify the clinical significance of RRM2 in glioma patients, firstly, we performed IHC staining analysis, and founded that compared with normal human brain tissues, RRM2, CDK1, and p62 protein expression had increase in distinct grades of glioma, especially in GBM tissues." (PMID 35651787, 2022). "While the CDK1 gene is overexpressed in glioma, which may promote the G2 phase transition of cells with DNA damage." (PMID 35677036, 2022). "Among them, CDK1 is required for successful completion of M-phase but also contributes to DNA-damage repair, checkpoint activation, and the progression of senescence escape by modulating the survivin pathway in glioma cells." (PMID 33723248, 2021). "Indeed, knockdown of CDK1 in several established GBM cell lines augmented the anti-glioma effect of TMZ resulting in decreased clonogenic survival following treatment with TMZ." (PMID 33707466, 2021). "Among TME-infiltrating male MG, we found cluster MG8 characterized by a high expression of genes encoding proliferation-related proteins (Stmn1, Tubb5, Tuba1b, Cdk1, and Top2a), which is consistent with the observed proliferation of MG within glioma TME, as previously reported." (PMID 33608526, 2021). "In the present study, sempervirine inhibited the activity of CDK1 and increased the expression of cyclin B1, we thus conjectured that sempervirine might affect CDK1-Cyclin-B kinase activity of glioma cells, and resulted in distinct cell cycle perturbation." (PMID 34916946, 2021). "By silencing FOXD2-AS1, cell cycle arrest and CDK1 downregulation were achieved in glioma cells." (PMID 32906592, 2020). "The FOXD2-AS1/miR-31/CDK1 axis has better therapeutic potential in glioma cells." (PMID 32906592, 2020). "Similarly, lncRNA FOXD2-AS1 promotes glioma progression through upregulating cyclin-dependent kinase 1 by sponging miR-31." (PMID 32977537, 2020). "Interestingly, previous research has marked that Cdk1/cyclin B overexpression in gliomas, marking it as a potential oncogene and highlighting the various apoptotic roles that Cdk1/cyclin B plays contingent upon Praja expression." (PMID 28966725, 2017). "Cdk1 (also named Cdc2) and cyclin B1 are also targets of the proteasome as evidenced from a study using geldanamycin, a drug interfering with the function of the chaperone protein Hsp90 (Heat shock protein 90), in glioma cells." (PMID 22817864, 2012). "Although this present work defined PKM2 as an integral component of the fundamental cell cycle regulatory complex in gliomas, PKM2 is over-expressed in other types of cancers, and most likely as like gliomas interaction of PKM2 with Cdk1 may play an important role in cell cycle progression." (PMID 35392228, 2022).
glioma (continued). "Therefore, in the current study, the downregulation of cyclin A2, cyclin B3, and CDK1 genes could prompt cell cycle arrest in U87 glioma cells." (PMID 28837560, 2017). "Western blot analysis showed elevated levels of cell cycle proteins B1, Cdk1, and pY15 after treatment, suggesting that compound 110’s antitumor activity in glioma may be due to its interference with the G2/M checkpoint, presenting a promising new direction for glioma therapies." (PMID 40001513, 2025). "Currently, CDK1 inhibitors, such as Rigosertib and Zotiraciclib, are in Phase III clinical trials and have shown potential in treating PDAC and gliomas." (PMID 40308776, 2025). "The upregulation of CCNB1, CDK1, CXCL8, IGFBP3, MYBL2, SERPINE1 also notably indicated poor overall survival of glioma patients (HR>1, P=0.000<0.05)." (PMID 34512164, 2021). "The anti-glioma effect of TMZ involves a complex response that includes G2-M cell cycle arrest and cyclin-dependent kinase 1 (CDK1) activation." (PMID 33707466, 2021). "This miR-31 sponging results in the overexpression of cyclin-dependent kinase 1 (CDK1), leading to glioma progression." (PMID 32906592, 2020). "In glioma, cell viability decreases significantly, possibly due to reduced expression of cyclin-dependent kinase 1(CDK1) protein, rather than apoptosis." (PMID 40216876, 2025). "Following this point of view, although the results of molecular docking supported the existence of affinity potential of TIZ with CDK1, CDK2, and CDK4, we only performed siRNA targeting CDK1 to verify the inhibitory effect of TIZ on the proliferation of gliomas." (PMID 35694267, 2022). "Besides, the positive correlation between Pontin and six E2F1 targets (AURKA, CDK1, CDK4, CCNA2, CCNB2, E2F8) assessed by GEPIA in glioma further supported the positive regulation of E2F1 targets expressions by Pontin." (PMID 33542204, 2021). "A negative correlation between miRNA-205 and CDK1 was observed in thymoma, brain lower grade glioma, colon adenocarcinoma, uterine corpus endometrial carcinoma, and breast invasive carcinoma." (PMID 33178832, 2020). "The effect of EPO on the proliferation of the U251 Cell glioma line in the hypoxia model was explored, the expression changes in the transcriptome were screened by high-throughput sequencing technology, and the differentially expressed genes PI3K, IKKα, and CDK1 were verified." (PMID 35167649, 2022). "Tyrosine-specific phosphoproteomic analysis of IL-33+ tumors showed an increase in a number of phospho-peptides derived from STAT3, CDK1, CDK2, FYN, MAPK14, and MAPK3, some that based on amino acid sequence could be attributed to either human glioma or mouse host origin." (PMID 33020472, 2020).
liver cancer (54 papers, 2014 to 2026). An epithelial or non-epithelial malignant neoplasm that arises from the liver. "The dysregulation of CDK1 has been closely associated with tumor progression, with elevated CDK1 levels observed in breast, stomach, colorectal, and liver cancers." (PMID 40534847, 2025). "CONCLUSIONS: MCA exerts anticancer effects in liver cancer cells by inducing cell cycle arrest via CDK1 downregulation and promoting apoptosis through a ROS-dependent oxeiptosis pathway." (PMID 41772680, 2026). "Through an in-depth study of the specific mechanism of CDK1 in liver fibrosis and liver cancer, it can provide a more accurate treatment plan for patients, improve the treatment effect, and reduce adverse reactions." (PMID 40332418, 2025). "In spite of some earlier research findings showing CDK1 as a prominent regulator of liver cancer, molecular docking studies have identified treatment options such the Phellodendron and Anemarrhena drug pair (PADP) as a promising inhibitor of CDK1." (PMID 41048345, 2025). "The combination of bioinformatics analysis, survival analysis and immune infiltration analysis has revealed the key role of CDK1 in liver fibrosis and liver cancer." (PMID 40332418, 2025). "These Q NPs effectively inhibited cell growth of liver cancer and colony formation by upregulating p27 and downregulating c-Myc, cyclinD1, cyclin-dependent kinase 1 (CDK1), matrix metallopeptidase 7, and β-catenin within the cancer cells." (PMID 40830621, 2025). "By inhibiting the activity of CDK1, it can slow down the progression of liver fibrosis and inhibit the growth of liver cancer, which can prolong the survival time of patients and improve the quality of life." (PMID 40332418, 2025). "Although CDK1 has demonstrated some potential in treating liver fibrosis and liver cancer, some limitations of the current study remain." (PMID 40332418, 2025). "Meanwhile, the conversion efficiency between preclinical studies and clinical trials needs to be improved to accelerate the clinical application of CDK1 inhibitors in the treatment of liver fibrosis and liver cancer." (PMID 40332418, 2025). "Different studies have some differences in the mechanism of CDK1 treatment for liver fibrosis and liver cancer." (PMID 40332418, 2025). "As a key regulator of the cell cycle, CDK1 plays an important role in the development of liver fibrosis and liver cancer." (PMID 40332418, 2025). "Bioinformatics tools, such as the Gene Expression Comprehensive Analysis (GEO) database and Gene Ontology (GO) analysis, provide us with a macro-to-micro perspective, revealing the key role of CDK1 in liver fibrosis and liver cancer." (PMID 40332418, 2025). "Cyclin-dependent kinase 1 (CDK1) is overexpressed in human liver cancer and liver-specific knockout (KO) of Cdk1 in mice prevents liver cancer." (PMID 40704506, 2025). "Cyclin-dependent kinase 1 (Cdk1) is a contributor to driving G2/M phase transition and has proven essential for cell proliferation and tumorigenesis in liver cancer." (PMID 36292952, 2022). "Costunolide upregulates Chk2 (Thr68), p-Cdc25c (Ser216), p-Cdk1 (Tyr15), and cyclin B1 in liver cancer (HA22T/VGH) cells." (PMID 35651747, 2022). "In vitro and in vivo studies, cell cycle progression was blocked by downregulate CDK1 in liver cancer cells in the G2-M phase." (PMID 36699068, 2022).